IL15 (interleukin 15)
Diseases named in the same sentence as IL15 in open-access papers (continued):
Sharing a sentence is not in itself a finding about the gene and the disease.
infection (continued). "However, expression of specific fibromodulatory interleukins (e.g., IL7, IL15, and IL20) was enhanced only in Chlamydia-infected HCECs, suggesting a cell type-specific response to infection." (PMID 37874141, 2023). "Infection of MDMs with non-opsonized bacilli induced, at least 10-fold, the synthesis of most tested cytokines except IL-15, IL-27, CCL2 and CCL7." (PMID 37781389, 2023). "Since the increase in total infection in IL-15-stimulated cells was more pronounced with R5 HIV-GKO than X4/R5 HIV-GKO, we hypothesized that IL-15 might enhance the expression of CCR5 compared to IL-2." (PMID 35499323, 2022). "The other two examined genes, IL11a and IL15, were down-regulatory expressed after SCRV infection." (PMID 36557717, 2022). "IL-15 significantly increases total infection in all the memory subsets but not in the naive T cells, possibly due to the lower expression of the IL-15 receptor in these cells than in the memory subsets." (PMID 35499323, 2022). "Overall, these data indicate that infection with R5/X4 HIV-GKO in the presence of IL-15 or IL-2 does not change the distribution of CD4+ T lymphocytes." (PMID 35499323, 2022). "Next, we analyzed the distribution of six CD4+ T cell subsets (naive, TSCM, TCM, TEM, TTM, and Temra) stimulated with IL-15 or IL-2 in the presence or the absence of R5/X4 HIV-GKO infection." (PMID 35499323, 2022). "For the analysis of the IL-15 BV or IL-15 BV + IL-15Rα BV infection in the absence of GFP, the secreted IL-15 protein or the complex were quantitated by IL-15 monomer-specific or IL-15:IL-15Rα complex-specific ELISA kits." (PMID 34439192, 2021). "The expression of IFN-γ, TNF-α, IL-15, and IL-17 secreted by pro-inflammatory Th1 and Th17 cells differed significantly between patients with and without this infection." (PMID 34026776, 2021). "IL-15 is a mucosal immune-related cytokine, and its expression is induced in dendritic cells (DCs) upon LPS or IFN-γ stimulation and is elevated in epithelial cells upon infection." (PMID 35054427, 2021). "DC isolated early after infection of pigs with either of the two CSFV strains showed prominent upregulation of CCL5, CXCL9, CXCL10, CXCL11, and XCL1, as well as of the cytokines TNFSF13B, IL6, IL7, IL12B, IL15, IL27." (PMID 32733474, 2020). "Since NK and CD8+ T cells were elevated following IL-15 treatment of CAST mice, it was important to determine whether both are necessary for early control of the infection." (PMID 32320436, 2020). "Infection in SD dams produced a significant increase in Il15 expression with no significant change in other cytokine/chemokine genes." (PMID 32884071, 2020). "We found that depletion of CD4+ and CD8+ T cells did not prevent the decrease in virus spread due to IL-15-treatment during the first week after infection but that T cells were necessary for virus clearance at later times." (PMID 32320436, 2020). "In the brains of PD-L1−/− mice a number of upstream regulators were enriched during acute infection but reduced or below threshold during persistent infection (e.g., IFN-γ, IL-15, NOS, NFATC2, and IL12-A), suggesting dynamic epigenetic changes in these genes in the absence of PD-1 signaling." (PMID 31105690, 2019). "To confirm a pivotal role of IL-15 in sustaining memory CD8 T cell inflation during MCMV infection, we infected naïve C57BL/6 and IL-15-/- mice with MCMV and followed endogenous M38-specific CD8 T cells over the course of infection in the blood." (PMID 29652930, 2018). "For example, IL1-β (gene IL1B) and IL23, which were markedly induced by Mtb in our infection model, are known to induce group 3 ILC (ILC3); IL15 among others activates ILC1 cells, and IL1-β, thymic stromal lymphopoietin (TSLP) and IL33 are prominent activators of ILC2 cells." (PMID 29977236, 2018). "In contrast, neither M. leprae infection not TLR2/1 activation of IL-15 MΦ induced upregulation OAS1 as a result of infection or following TLR2/1 stimulation." (PMID 30300363, 2018).
infection (continued). "Vitamin D status did not alter the phagocytic function of IL-15 MΦ, but a significant decrease in bacteria burden against M. leprae was observed at 120 hours post-infection." (PMID 29965969, 2018). "To examine the association of circulating common γ-chain cytokines with TB disease or infection, we examined the systemic levels of IL-2, IL-7, IL-15, and IL-21 in individuals with PTB, latent TB (LTB) or no TB infection (NTB)." (PMID 28448542, 2017). "Mice that were immunized with plasmids encoding Leader-Gag and Env and the cytokines IL1β, IL12, IL15, IL28A or GM-CSF, but not Leader-Gag and Env without any cytokine, showed significantly reduced viral loads upon a high-dose Friend virus challenge infection." (PMID 28449719, 2017). "There was significant induction of bronchial IFN-γ, CXCL11/ITAC, CXCL10/IP10, IL-15, IL-10, TNFα and IL-5 during infection in allergic asthmatics (all P < 0.05), but not in healthy controls." (PMID 28373098, 2017). "Treatment with IL-15 SA did not modify post-infection cytokine production when compared to vehicle-treated mice." (PMID 26859674, 2016). "Treatment with IL-15 SA did not alter bacterial clearance in either the burn wound or systemic infection models nor did it effect neutrophil recruitment to the site of infection in mice receiving intraperitoneal Pseudomonas challenge." (PMID 26859674, 2016). "Infection significantly lowered the core body temperature of mice, both with and without IL-15 SA treatment." (PMID 26859674, 2016). "When BHK21 cells were infected at a MOI (multiplicity of infection) of 10, the culture supernatant of MVA-CSP/IL-15 infected cells contained approximately 2ng/ml of human IL-15 whereas the culture supernatant of MVA-CSP infected cells had no detectable human IL-15 (data not shown)." (PMID 26505634, 2015). "Unfortunately, the role of this burst in sIL-15 complexes early in an infection is unclear as there is presently no in vivo model that allows one to distinguish IL-15 responses mediated by sIL-15 complexes from those mediated by transpresentation." (PMID 25756182, 2015). "We did not include a control group of animals that received anti-IL15 administration alone during acute infection since such a study has already been conducted by the Picker lab." (PMID 24603870, 2014). "Previously we and others have shown that a variety of cytokines and chemokines were induced by both HRV 14 and/or HRV 16 infection in vitro that include FGF-Basic, chemokines and cytokines like IL-6, IL-15, MCP-2, IP-10, MIP-1β, type I IFN-α, type III IFN-λ2 (IL-28A), and ENA-78." (PMID 25500821, 2014). "Plasma levels of α-defensins, IL-10 and IFNγ peaked in the acute phase of infection, whereas IL-15 showed fluctuation throughout the study (data not shown)." (PMID 24695530, 2014). "Because IL-15−/− mice exhibit a severe developmental defect in both NK and NKT cell lineages and are nearly devoid of these cell populations, we chose to use an anti-IL-15 blocking antibody to selectively deplete IL-15 concurrent with infection." (PMID 22624047, 2012). "MRNA levels of genes encoding for chemokines (CXCL1 and CXCL5), cytokines (IL-10, IL-15 and IL-32), pattern recognition receptors (TLR1) and innate signaling molecules like IRAK3 and TRAF6, were all increased after MVA-C infection in comparison with MVA-WT-infected cells." (PMID 22536391, 2012). "Therefore, we believe that an abrogation of virally-induced IL-15 in the lung airways most dramatically affects CD3−, NK1.1, NKp46 double positive NK cells responding rapidly to infection." (PMID 22624047, 2012). "After 48 h of infection, MVA-B induced higher production of IL-7, IL-15, MCP-1/CCL2 and MIG/CXCL9 than uninfected MDDC, indicating that some mediators are secreted at later times post-infection and/or at low doses possibly because is necessary some degree of maturation to up regulate such mediators." (PMID 21625608, 2011).
infection (continued). "Peak viremia post-infection, however, was not affected, and this is similar to IL-15 and IL-12 administration during acute infection." (PMID 21852945, 2011). "IL-15 levels in vivo were also significantly related to virus loads in nasal lavage (r = −0.57, p = 0.005), induced sputum (r = −0.44, p = 0.041) and BAL (r = −0.61, r = 0.024) upon subsequent in vivo RV16 experimental infection in the same subjects." (PMID 21779162, 2011). "Furthermore, neutralization of IL-12 by Ab-treatment prior to infection completely prevented NK cell IFN-γ production in both WT and IL-15−/− mice." (PMID 20213736, 2010). "Our results contrast with earlier findings obtained in other infection models using viral, bacterial or fungal pathogens, where IFN-α/β and/or IL-15 enhanced the activation of NK cells or were critical for NK cell IFN-γ production and/or for NK-cell cytotoxicity 1,9,22,25,26." (PMID 20213736, 2010). "Ex vivo infection of human gestational membranes with GB112 resulted in significantly elevated production of IL-15, M-CSF, MCP-3, and MIP-1β—results that were not seen in either the maternal or fetal chamber of the organ-on-a-chip model, as determined by one-way ANOVA with Tukey’s post hoc test." (PMID 41277827, 2025). "Therefore, lower expression of IL-12 (p70) and IL-15 in VBT patients could lead to lower NK cell activation, promoting viral dissemination at an early stage of infection." (PMID 37261350, 2023). "Indeed, we observed that the most considerable augmentation of pro-inflammatory IL-1β, IL-6, IL-15, IL-18, IFN-γ, eotaxin, GRO-α, IP-10, MCP-1, MIP-1α, MIP-1β, and regulatory IL-1RA, occurred at the terminal stage of the disease (7 days post-infection) in our rhesus macaques." (PMID 38035334, 2023). "IL-15 increases R5 HIV-GKO total infection, with no impact on cell viability." (PMID 35499323, 2022). "Infection with either virus led to enhanced expression of the inflammatory chemokines CCL5, CXCL10 and CXCL11, whereas mRNA expression levels of IL-6, IL-12 and IL-15 were only increased in MAYV-infected cells." (PMID 33799906, 2021). "The profound down-regulation of the T-lymphocyte inducer IL-15 throughout early HCV infection in macrophages could provide a hint towards such a response, as the reduced expression of IL-15 could result in blunted T-cell responses later in infection." (PMID 34571900, 2021). "Whether or not sufficient levels of IL-15 to activate neonatal NK cells would be present at sites of infection will require additional research." (PMID 32373131, 2020). "Finally, a marked increase in inflammatory chemokines MIP-1β/CCL4, MCP-1/CCL2, and IL-8/CXCL8, accompanied by an increase of inflammatory cytokines IL-15, IL-12, TNF-a, GM-CSF, and G-CSF, which was detected in the lung predominantly at day 7–9, the middle and late stage of infection." (PMID 33180882, 2020). "Following oral infection of pig with T. gondii oocysts, a significant increase in IFN-γ, IL-15, TNF-α, and inductible-NO gene expressions, in lymph nodes draining sites of infection colonic lymph nodes (CLNs), jejunal Peyer’s patches (PPs) and MLNs, was observed at 7 days post-infection." (PMID 33324583, 2020). "Many tissue-specific cytokines including IL-15, TGF-β, IL-12, and type I IFN are produced upon infection and inflammation and regulate differentiation and persistence of Trm cells in non-lymphoid tissues, with differential requirements that may be tissue specific." (PMID 30108585, 2018). "However at 120 hours post infection the relative bacteria burden significantly decreased to 0.67 and 0.44 in IL-15 MΦ differentiated in 10-8M and 10-7M 25D3 compared to no 25D3, respectively." (PMID 29965969, 2018). "Many tissue-specific cytokines including IL-15, TGF-β, IL-12, and type I IFN are produced upon infection and inflammation and regulate differentiation and persistence of Trm cells in non-lymphoid tissue, with differential requirements that may be tissue specific." (PMID 30108585, 2018).
infection (continued). "Thus, treatment with IL-15 SA did not provide a sustained elevation in lymphocyte numbers after infection, which was reflected in its inability to augment antimicrobial immunity in our model." (PMID 26859674, 2016). "The molecules that depicted significant increases in those mAb treated-mice at 96 h after infection were CXCL1 (KC), CCL2 (MCP-1), CCL3 (MIP-1α), CCL4 (MIP-1β), CXCL2 (MIP-2), CXCL5 (LIX), IL-1α, IL-6, G-CSF, M-CSF, and TNF-α (for all, P < 0.01) and IL-1β, IL-15, IL-10, and LIF (for all, P < 0.05)." (PMID 27642235, 2016). "However, the therapeutic efficacy of IL-15 or IL-15 superagonist (SA) during infection after burn injury has not been evaluated." (PMID 26859674, 2016). "Moreover, this treatment increased the production of IL-12, IL-23, IL-27, IL-15, and IL1β such that negative correlations between the levels of these cytokines with both the infection ratio and number of intracellular parasites were observed." (PMID 26488744, 2015). "However, they demonstrate that other non-γ-chain cytokines such as IL-12 during infection can stimulate NK expansion and activity independent of IL-15." (PMID 25197644, 2014). "For the cytokines FGF basic and IL-15 the addition of PBMCs did not significantly change the levels and for IL-6 the addition of PBMCs did not affect the relative differences between the levels associated with HRV 14 and HRV 16 infection." (PMID 23799120, 2013). "We investigated regulation of IL-15 induction by rhinovirus in human macrophages in vitro, IL-15 levels in bronchoalveolar lavage (BAL) fluid and IL-15 induction by rhinovirus in BAL macrophages from asthmatic and control subjects, and related these to outcomes of infection in vivo." (PMID 21779162, 2011). "Importantly, we demonstrate for the first time that MDDC infected with MVA and MVA-B, secrete IL-7 and IL-15 at levels more than 30-fold higher than the negative control after 48 h post-infection without maturation cocktail." (PMID 21625608, 2011). "This is also true for IL15 at 6 h and 24 h after infection (data not shown)." (PMID 21629653, 2011). "Taken together, our data suggests that IL-7 and IL-15 have overlapping roles in mediating up-regulation of Bcl-2 and CD127 on antigen-specific CD8+ T cells and that differential CD127 expression does not impede CD44 expression or effector functions during acute phase infection." (PMID 20520779, 2010). "Further, our data suggests that absence of IL-15 alone may play a minor role in committing CD8+CD44int/hiCD127hi T cells to express Bcl-2 during the acute phase of infection." (PMID 20520779, 2010). "In this study, we tested the hypothesis that administration of ART and viral Envelope-specific rhesus-derived IgG1 monoclonal antibodies (RhmAbs) with or without the IL-15 superagonist N-803 early in infection would limit viral reservoir establishment in SIV-infected infant rhesus macaques." (PMID 39792949, 2025). "Thus, in HIV/TB patients, low plasma levels of IL-15 may reflect a systemic long-term effect of Mtb infection on the immune system regardless of the infection course." (PMID 37376629, 2023). "The impaired MHC-I upregulation in Ly6ChiCCR2hiCD11b+ monocytes of Il15-/- and Ifng-/- mice could not be attributed to the high bacterial load, as it was not affected in WT-HD mice with high bacterial load achieved by high dose infection." (PMID 34956227, 2021). "While we know that constitutive levels of IL-15 and IL-7 maintain homeostatic memory CD8 and CD4 T cell populations, the role of high levels of PRR-signaling such as that leading to type I IFN and other proinflammatory cytokines during active infection remains unclear." (PMID 29632538, 2018). "IL-18, in contrast to IL-15, does not influence the development or homeostasis of NK cells, but French and colleagues demonstrated that the IL-18 receptor is constitutively expressed on splenic NK cells and IL-18 contributes to NK cell proliferation during infections." (PMID 28904191, 2017).
infection (continued). "However, IL-15 SA predominantly expands NK, NKT, and mCD8+ lymphocytes, whereas preferential expansion of naïve and effector CD4 and CD8 T-lymphocyte populations, with therapies such as IL-7, may provide more effective resistance to infection." (PMID 26859674, 2016). "However, they did not determine the effect of IL-15/IL-15Rα in the frequency of the different NK cell maturation subsets as determined by CD27 and CD11b expression or the NK cell protective function during a pathogenic infection." (PMID 25399821, 2015). "In order to determine whether an absence of IL-15 in the lung airways resulted in the reduced frequencies and numbers of NK cells specifically, numbers of other populations of innate cells in the airways at these early time points post infection were analyzed." (PMID 22624047, 2012). "We observed 80% survival in WT GMP‐transplanted mice after infection but no survival of IL15RA‐KO GMP‐transplanted mice (50,000 GMPs for each genotype), demonstrating that IL‐15 signaling from myeloid cells was required for NK cell support." (PMID 37635627, 2023). "On the other hand, no significant increase in IL-15, G-CSF, or IFN-γ levels was detected following challenge infection in the rDIs-S-vaccinated macaques." (PMID 36466631, 2022). "In presence of IL-2 and IL-15 there was a significant increase in MIP-1α levels and RANTES had near significance (P = 0.0512) at 12 h post-infection (p.i.)(data not shown)." (PMID 30405602, 2018). "On the other hand, CYP27B1 gene expression in IL-15 MΦ, which have high CYP27B1 gene expression at baseline, was not significantly affected as a result of either infection or stimulation with exogenous TLR2L." (PMID 30300363, 2018). "Moreover, the increase of CD25 membrane expression seen after infection may imply that cells with higher CD25 levels, in an environment poor in cytokines critical for their differentiation, can keep a relative efficiency for the IL-2- or IL-15-dependent signaling pathways." (PMID 26745276, 2016). "With this system, we noted differences in cytokines and chemokines, like FGF-Basic, IL-15, IL-6, IL-28A, ENA-78 and IP-10 without PBMCs and MIP-1β, IL-28A, MCP-2, and IFN-α with PBMCs between HRV 14 and 16 during infection of calu-3 cells." (PMID 25500821, 2014). "Therefore, we measured the secretion of pro-inflammatory (IL-8, IL-12a, IL-15, IL-6) cytokines by qPCR at different times after HKDM infection with WT and ∆EseN mutant, and uninfected HKDM as a negative control." (PMID 35889053, 2022). "Therefore, we investigated expression of IL-15 and ISGs, such as APOBEC3G, ISG15, ISG20, MX1, MX2, and RSAD2, after infection with R5-tropic, non-opsonized (HIV) and complement-opsonized (HIV-C) HIV-1 strains (BaL and YU-2)." (PMID 34634939, 2021). "Regardless of the infection, TNF-α, IL-15, IL-18, and CCL-5 were absent or barely detected." (PMID 30420629, 2018). "Because of the mild infection in the lungs of non-drug-treated/SeV-infected mice, an attenuated inflammatory response in BALF resulted in only IL-13 and IL-15 (out of the 32 tested) being significantly increased compared to PBS-inoculated control mice (P < 0.01)." (PMID 27589232, 2016).